RETN (resistin)
Diseases named in the same sentence as RETN in open-access papers (continued):
Sharing a sentence is not in itself a finding about the gene and the disease.
Obesity (continued). "The resistin secreted by adipose tissue is also closely related to tumor progression, and it is also an important bridge connecting obesity and insulin resistance." (PMID 34485124, 2021). "In 2001, resistin, for ”insulin resistance”, was labeled as a potential mediator between obesity and diabetes." (PMID 34944905, 2021). "Interest for resistin as a link between obesity and diabetes originated from the observations of increased insulin sensitivity in response to reducing resistin levels in obese mice." (PMID 33716966, 2021). "In contrast, administration of resistin-neutralizing antibodies in a mouse model of obesity and insulin resistance led to significant improvements in sensitivity to insulin 4,5." (PMID 34659568, 2021). "It is documented that adipocytes express and secrete an array of adipokines including leptin and resistin, which are involved in the pathogenesis of obesity and type 2 diabetes." (PMID 34063048, 2021). "Future research is necessary to decide on the utility of targeting resistin for obesity interventions." (PMID 34680059, 2021). "This is likely to be the reason that resistin levels in plasma are reported to be elevated in obesity and diabetes." (PMID 33679451, 2021). "Its level increases with obesity, with central obesity in particular, contributing to rising levels of resistin." (PMID 34436493, 2021). "During obesity, the adipocytes accumulate more lipids and secrete increased levels of proinflammatory adipokines (leptin and resistin) and reduced levels of anti-inflammatory adipokines (adiponectin)." (PMID 33917607, 2021). "Collectively, the limited literature suggests an emerging role for resistin in suppressing myogenic differentiation, particularly in older skeletal muscle, which appears to be driven by inflammation and obesity." (PMID 33528828, 2021). "In animal models, increased levels of resistin induced hyperglycemia associated with elevated hepatic glucose production while the reduction in resistin prevents obesity-related hyperglycemia due to increased insulin sensitivity." (PMID 34202323, 2021). "In the general population resistin is being associated with LVDD and all the clinical conditions (diabetes, obesity, hypertension), predisposing to it." (PMID 33684166, 2021). "Literature about the role of Resistin in insulin sensitivity and obesity is controversial due to the difference between human and rodent resistin." (PMID 34209146, 2021). "The inflammatory adipokine resistin is elevated in obesity and has an important role in insulin resistance." (PMID 33738261, 2021). "Their study verified that obesity-related resistin facilitated BC progression by induction of EMT and stemness properties of BC cells via activating TLR4/NF-κB/STAT3 signaling in animal models of BC tumorigenesis and metastasis." (PMID 34350120, 2021). "In rodents, circulating levels of resistin are increased in obesity, and have been demonstrated to play a role in mediating hepatic and skeletal muscle insulin resistance and in the regulation of glucose metabolism through AMP activation." (PMID 34496965, 2021). "In humans, the main source of resistin is macrophages and in obesity it is the macrophages that have infiltrated into visceral white adipose tissue." (PMID 33679451, 2021). "Resistin, a 12.5 kDa protein encoded by the RETN gene, is related to obesity, inflammation, and various cancer type, including BC." (PMID 34350120, 2021). "Weighted mean differences (WMDs) with corresponding 95% confidence intervals (CIs) were calculated to evaluate the strength of the association between the levels of resistin and follistatin with PCOS in the overall and stratified analysis by obesity status." (PMID 33740002, 2021). "Concretely, the adipokines, such as leptin, adiponectin, resistin, and other adipokines like visfatin, secreted frizzled-related protein 5 (SFRP5), play an indispensable role in the manipulation of obesity-associated BC." (PMID 34350120, 2021).
Obesity (continued). "Increased resistin level is also consistent with our phenotype as this hormone mediates insulin resistance and links obesity to T2D in mice and men69,70." (PMID 33772116, 2021). "The plasma levels of resistin levels are increased in obesity and diabetes and several human studies indicate a relationship between plasma resistin levels and increased obesity." (PMID 33679451, 2021). "In parallel with increased visceral adiposity, the rise in circulating leptin and resistin levels exacerbates the local inflammation of adipose tissues, leading to obesity-related insulin resistance." (PMID 34579036, 2021). "This relationship with microbiota dysbiosis is further supported by elevated levels of resistin and PAI-1, adipokines associated with obesity and T2D." (PMID 33467110, 2021). "The levels of adipocyte-derived hormones, leptin, resistin and adiponectin, depend on the fat mass and are involved in the endocrine, immunological and metabolic complications of obesity." (PMID 33658532, 2021). "Resistin, originally referred as the adipose-tissue-specific secretory factor (ADSF), is an important adipokine that links obesity, inflammation, IR, and diabetes." (PMID 34681797, 2021). "Similar to leptin and visfatin, other adipokines overexpressed in obesity, such as resistin, apelin, and chemerin, also possess some oncogenic functions." (PMID 33535537, 2021). "In diet-induced obesity, as well as in animal models of obesity and insulin resistance, the level of resistin significantly increases." (PMID 33322719, 2020). "A meta-analysis showed that pediatric subjects with obesity exhibit reduced resistin levels following aerobic exercise." (PMID 32158768, 2020). "Adiponectin and resistin are typically secreted by the adipose tissue and are abnormally expressed in obesity." (PMID 32586265, 2020). "We focused our next investigation of TAZ/Resistin and breast cancer on TNBC, which also showed the most significant association between obesity and clinical T stages." (PMID 33318171, 2020). "Given the strong relationship between inflammation and metabolism, there is mounting evidence suggesting a role for human resistin in the pathological processes of metabolic diseases, including obesity, diabetes, and cardiovascular diseases." (PMID 32762639, 2020). "The resistin is released from infiltrating white blood cells subsequent to subclinical chronic low-grade inflammatory response, accompanying obesity." (PMID 32393214, 2020). "In line with this, we previously demonstrated enhanced secretion of resistin by adipocytes during obesity-related conditions in a preclinical study." (PMID 32560703, 2020). "In children, high levels of leptin and insulin are often associated with low levels of adiponectin and high levels of resistin, as obesity is a condition that modulates the secretion of both adipokines, which exacerbates insulin resistance." (PMID 33266497, 2020). "Among these adipokines, circulating resistin levels have been reported to be positively correlated with obesity and incidence of postmenopausal breast cancer." (PMID 32560703, 2020). "Resistin is a member of cysteine-rich protein which appears to increase in T2D, obesity, and insulin resistance; resistin promotes insulin sensitivity through TNF-alfa and IL-6 activation." (PMID 32481506, 2020). "Metabolic abnormalities within adipose tissue can contribute to obesity complications including excess adipokine secretion: visfatin, leptin, and resistin, but also TNF-α as and plasminogen activator inhibitor-1 (PAI-1)." (PMID 32963689, 2020). "Among the metabolic components linking obesity and cancer, adipokines, especially adiponectin, leptin, and resistin, existing in BMF, are known to induce tumorigenesis." (PMID 33112535, 2020). "Resistin is a pro-inflammatory adipokine that positively correlates with hyperglycemia and insulin resistance in obesity, and both peripheral and hypothalamic administrations of resistin impair insulin signaling." (PMID 33097799, 2020).
Obesity (continued). "According to the effect of decreased weight and WC previously reported in patients with grade I and II obesity treated with dapagliflozin, we expect a decrease in resistin and IL-6 concentrations and an increase in IL-10 and adiponectin concentrations." (PMID 32059692, 2020). "Plasminogen activator inhibitor-1 (PAI-1) showed an increase (p < 0.001), C3, an immune marker was significantly decreased (p < 0.01) and resistin, an adipokine involved in obesity and Type-2 diabetes, was also significantly decreased (p < 0.05)." (PMID 33383677, 2020). "Conversely, some studies have shown that adipose tissue-derived resistin is suppressed in obesity, inciting the controversy over what role resistin plays in obesity that persists today." (PMID 32158768, 2020). "Leptin and resistin present a similar behavior and can be found in high levels in conditions such as obesity and breast cancer." (PMID 32903534, 2020). "Resistin, also known as adipocyte-specific secretory factor or FIZZ3, is a protein rich in cysteine with a controversial physiological role in obesity and insulin resistance." (PMID 33419284, 2020). "These initial studies led to the suggestion that resistin plays an important role in modulating insulin resistance in the context of obesity, and it has been shown to correlate with insulin resistance in mice and humans." (PMID 32158768, 2020). "Adipocytokines, such as resistin, are correlated with obesity, acting in the regulation of blood glucose, homeostasis, and insulin resistance." (PMID 32903534, 2020). "Some studies have shown that elevated levels of serum resistin lead to metabolic disorders, including obesity, insulin resistance, type 2 diabetes, hypertension, dyslipidemia, and atherosclerotic cardiovascular disease." (PMID 32143662, 2020). "Obesity is a chronic low-grade inflammation, and the concentrations of resistin, leptin, and IL-1β, as well as TNF-α and IL-6, in peripheral blood of obese patients were significantly increased." (PMID 32104715, 2020). "The suggested mechanism by which the resistin affects obesity and insulin homeostasis acts on target cells both via paracrine and endocrine signaling pathways and via its receptors." (PMID 33182462, 2020). "Earlier data concerned the relationship between resistin and obesity, type 2 diabetes mellitus, and atherosclerosis." (PMID 33202617, 2020). "More specifically, studies on the potential outcome of NSPT on the periodontal parameters, serum resistin level, and periodontal pathogens counts in periodontitis with obesity remains largely scanty." (PMID 32059714, 2020). "Specifically, GG genotypes of rs3219175 and rs34861192 of the Resistin (RETN) gene, encoding a hormone that links obesity to diabetes mellitus, were associated with increased risk of small artery ischemic stroke." (PMID 33352859, 2020). "Our data show that VGVAPG peptide altered the expression profile of Pref-1, serpin E1, adiponectin, VEGF, and resistin which are the key proteins involved in developing obesity and/or insulin resistance." (PMID 32463311, 2020). "Adipose tissue-secreted hormones such as leptin and resistin have significant roles in the initiation and progression of many metabolic disorders such as obesity and diabetes." (PMID 33007981, 2020). "The adipose tissue is a source of several hormones of which the adipokines - leptin, adiponectin, resistin, and omentin - play important roles in the pathophysiology of obesity and diabetes in humans." (PMID 31533709, 2019). "In obesity, there is an expansion of white adipose tissue which is the primary site that produces adipokines such as leptin, resistin, and adiponectin." (PMID 31316526, 2019). "Obesity is associated with inflammation and inflammatory cytokines including TNF-α, IL-6 and resistin promote phosphorylation of insulin receptor substrates 1 (IRS-1) at serine sites that negatively regulates normal insulin signaling." (PMID 31226166, 2019).
Obesity (continued). "Circulating levels of resistin positively correlate with obesity in rodents, promoting both inflammation and insulin resistance." (PMID 30906281, 2019). "This study shows the possibility of using psoriasin, nestin, Krt16, and IL-21 as biochemical markers of psoriasis and highlights the correlation of these with biomarkers of obesity (BMI, leptin, and resistin)." (PMID 31275060, 2019). "The effects of obesity on adipocytes include upregulation of pro-inflammatory adipokines such as leptin and resistin, downregulation of anti-inflammatory adipokine, and also the stimulation of pro-inflammatory cytokine production by macrophages." (PMID 31316526, 2019). "Circulating levels of resistin were increased in genetic and diet-induced obesity and were decreased by treatment with anti-diabetic drug rosiglitazone." (PMID 31208019, 2019). "Concerning resistin, it has been reported that it increases because of obesity and significantly reduces by exercise and caloric restriction." (PMID 30654813, 2019). "Different experimental and clinical researches identified the TLR4 signaling pathways activated by resistin as the molecular mechanism that links insulin resistance and obesity." (PMID 31772701, 2019). "The findings of some studies indicate that T3 modulates the gene expression, serum levels of leptin, resistin, and adiponectin in obesity." (PMID 31666810, 2019). "The evidence regarding the role of resistin in obesity and MS in children has been shown to be conflicting." (PMID 31404407, 2019). "The adipokines leptin, resistin, and TNF-α are also involved in lipid and glucose metabolisms, and their enhanced expressions have been linked with the development of diabetes and obesity." (PMID 30863274, 2019). "Further investigations are needed to clearly decipher regulatory mechanisms involved in hypothalamic resistin/TLR4 signaling in the context of obesity." (PMID 30906281, 2019). "The objective was to establish if psoriasin, nestin, Krt16, and IL-21 were possible biomarkers of psoriasis and to correlate them with Body Mass Index (BMI), leptin, and resistin (biomarkers of obesity)." (PMID 31275060, 2019). "During the past few years, many advances have been made in our understanding of the relationship between resistin and obesity." (PMID 30809105, 2019). "Experimental data show that in rodent models of diet-induced obesity, or in the case of genetic forms of obesity, blood resistin levels are elevated." (PMID 31623226, 2019). "Some studies report comparable adiponectin, leptin and resistin levels in PCOS whiles others report lower adiponectin, higher leptin and resistin levels among women with PCOS than controls in relation to obesity." (PMID 31416473, 2019). "Adipokines such as leptin and resistin have been found to be consistently increased in both adults and children with obesity and the MS, contributing to insulin resistance." (PMID 31404407, 2019). "Obesity is a chronic low-grade inflammatory condition accompanied with the increased production of various inflammatory factors including resistin." (PMID 30050954, 2018). "We also evaluated the plasma levels of different obesity and T2D markers such as adiponectin, leptin, resistin, visfatin, PAI-1, and insulin." (PMID 30131766, 2018). "These inflammations increase the expression of TNF-α and NF-κB, and affect the secretion of metabolic hormones, such as insulin, adiponectin, leptin, and resistin, promoting obesity." (PMID 29707542, 2018). "Above all, resistin played an important role in the process of lipid metabolism and inflammation in obesity." (PMID 30398974, 2018). "Resistin was initially identified in white adipocytes of mice, and the serum level of resistin was found to be more remarkable in animal models of obesity and insulin resistance." (PMID 29848323, 2018).
Obesity (continued). "Previous reports show that pro-inflammatory resistin is significantly increased in serum but reduced in the white adipose tissue of diet-induced as well as genetic models of obesity." (PMID 30369883, 2018). "Resistin is an adipocytokine that, although controversial, has been considered as the main variable explaining the relationship between obesity and IR." (PMID 30513771, 2018). "Taken together, these results suggest that soyasapogenol B exerted an anti-obesity and anti-diabetic effect on adipocytes by lowering the cellular triglyceride level by accelerating triglyceride lipolysis with reduced resistin secretion." (PMID 30294680, 2018). "They demonstrated that resistin, leptin, and TNF-α are associated, independently of obesity and waist circumstance, with chronic venous disease." (PMID 29720688, 2018). "In order to confirm our newly proposed Type II MHO model, i.e., the designation of MHO being converted to classically unhealthy obesity, we probed for pro-inflammatory resistin in adipose tissue of MHO model." (PMID 30369883, 2018). "Levels of resistin, secreted by macrophages and white adipose tissue, are elevated in human subjects with obesity." (PMID 29371863, 2018). "The correlation between plasma resistin with both obesity and insulin resistance in humans support a role for resistin in the development of insulin resistance." (PMID 29760587, 2018). "Resistin is a novel adipokine identified that suppresses glucose tolerance and insulin sensitivity, and has been proposed to be an important link between obesity, insulin resistance and type 2 diabetes (T2D)." (PMID 30524378, 2018). "Adipose tissue is an active secretory organ whose secretion profile drastically changes with overweight and obesity, increasing the circulating concentrations of adipokines like leptin, or resistin." (PMID 28542472, 2017). "The significant reduction in resistin production after the MED-diet intervention is of biological relevance since elevated resistin is associated with insulin resistance, CVD risk and obesity." (PMID 29312949, 2017). "In the animals’ serum, resistin is consistently higher in obesity, and there is a clear relationship between resistin levels and insulin resistance." (PMID 28661458, 2017). "Here, we found a decrease in the adipose expression of both resistin and adiponectin in obese mice prior to stroke, as has been previously reported in obesity." (PMID 28798136, 2017). "Other molecules produced by adipose tissue(adipokines) such as visfatin and resistin, also related to diabetes and obesity were measured." (PMID 28425473, 2017). "Circulating levels of resistin are increased in obesity, and epidemiological studies suggested a link between resistin levels and cancer risk." (PMID 28915700, 2017). "Our data indicate a link between low circulating levels of TRAIL and markers of obesity-induced diseases (resistin and lipocalin-2/ngal), highlighting a new potential axis of TRAIL functions." (PMID 29056829, 2017). "Leptin- and resistin-exhibited elevated levels are positively correlated with obesity and its complications." (PMID 29142618, 2017). "Taking into consideration that diabetes mellitus and obesity are major characteristics of MetS, the resistin gene was considered as a potential candidate gene for MetS in this study." (PMID 29386698, 2017). "Reportedly, while adiponectin expression levels decrease with increase in the adiposity, lepin and resistin levels increase in obesity." (PMID 28953247, 2017). "In mice, resistin was proposed as a possible link between obesity and insulin resistance; however, its exact role in the pathogenesis of type 2 diabetes in human is still a matter of debate." (PMID 29138754, 2017). "In one study, diet-induced obesity was investigated in humanized resistin mice, which are transgenic mice producing resistin mainly from macrophages in a way similar to human." (PMID 29138754, 2017).